CASZ1 (castor zinc finger 1)
Diseases named in the same sentence as CASZ1 in open-access papers (continued):
Sharing a sentence is not in itself a finding about the gene and the disease.
tumor (continued). "Castor Zinc Finger 1, a transcription factor, may function as a tumor suppressor and controlling cell fate, a Putative survival-related protein." (PMID 32874429, 2020). "The low expression of CASZ1 was significantly correlated with old age (>55 years) (p = 0.037), large tumor size (p = 0.004), high WHO/ISUP grade (p < 0.001), and high T category (p < 0.001) and M category (p = 0.008) but not correlated with gender or N category." (PMID 31481981, 2019). "Some studies showed that CASZ1 has a role in tumor progression." (PMID 31481981, 2019). "Finally, we proved that CASZ1 exerted its tumor-suppressive effect by directly interacting with RAF1 and reducing the protein stability of RAF1." (PMID 29506567, 2018). "In addition, downregulation of CASZ1 (ANLT/HCC > 2) was detected in 34 of 50 (68%) HCCs compared to their matched adjacent non-tumor liver tissues (ANLTs)." (PMID 29506567, 2018). "Previous studies have reported the controversial roles of CASZ1 in several cancers, which may be related to tumor and tissue specificity." (PMID 29506567, 2018). "Our study for the first time demonstrated that CASZ1 is a tumor suppressor in HCC, which may serve as a novel prognostic predictor and therapeutic target for HCC patients." (PMID 29506567, 2018). "In the present study, our findings were in accordance with Liu’s report, and strongly demonstrated that CASZ1 is a tumor suppressor in HCC, which may be a potential therapeutic target for HCC." (PMID 29506567, 2018). "Furthermore, the in vivo animal experiments demonstrated that CASZ1 overexpression not only inhibits tumor growth, but also suppresses HCC metastasis, as determined by IVIS detection and H&E staining." (PMID 29506567, 2018). "The zinc finger transcription factor CASZ1 has been found to control neural fate-determination in flies, regulate murine and frog cardiac development, control murine retinal cell progenitor expansion and function as a tumor suppressor gene in humans." (PMID 26296975, 2015). "CASZ1, a neuronal differentiation gene, have been shown to possess tumor suppressor activity." (PMID 22928040, 2012). "The complex role of CASZ1 in malignant tumors may be related to tissue and tumor specificity." (PMID 38053207, 2023). "Thus these findings together defined CASZ1 as a tumor suppressor in HCC, which may be a novel prognostic biomarker and therapeutic target for HCC patients." (PMID 29506567, 2018). "No tumor-associated nucleotide mutations have been reported in the CASZ1-coding sequence, suggesting that mechanisms such as epigenetic silencing may be associated with reduced CASZ1 expression in tumors from patients with poor prognosis." (PMID 38053207, 2023). "Several of these EPINs have promoters of differentially expressed genes (such as DLL1, STOM and SEC11C in the GEPIA tumor/normal dataset; ID2, RPS27, SEC11C, CASZ1, CRTC2, C5 and STOM in the LNCaP/LHSAR dataset; see Methods, Differential Gene Expression)." (PMID 38057321, 2023). "Additionally, we analyzed CASZ1 expression patterns in other solid tumors from TCGA and observed that there was a degree of variability in the expression of CASZ1 across different tumors, which suggested that CASZ1 seemed to play distinct roles in the different tumor types." (PMID 36276925, 2022). "In particular, cg20288000 site is found in an enhancer of CASZ1, a gene coding for a TF that is involved in different cancers, including epithelial ovarian cancer consistent with the notion that hypermethylation of enhancers may be observed after reduced ER activity in tumours." (PMID 34403459, 2021). "At least five genes located at 1p36 (CHD5, CAMTA1, KIF1B, CASZ1, and MIR34A) were already suggested to be tumor suppressors." (PMID 34956867, 2021). "We further evaluated mRNA levels of CASZ1 by RT-PCR in normal skeletal muscle samples and RMS tumor samples." (PMID 32060262, 2020).
tumor (continued). "As the downstream effectors of p-ERK, MMP2 and MMP9 are important for tumor invasion and metastasis by degrading basement membrane components, while cyclinD1 acts on G1-S progression of the cell cycle, thus they may decipher the function of CASZ1 in HCC proliferation and metastasis." (PMID 29506567, 2018). "To verify the capacity of CASZ1 to inhibit HCC progression in vivo, we established subcutaneous xenograft tumor models and orthotopic xenograft tumor models using luciferase-labelled HCCLM3CASZ1, PLC/PRF/5shCASZ1 and their control cells." (PMID 29506567, 2018). "Immunohistochemical analysis revealed that CASZ1 staining, mainly localized to the cytoplasm in the hepatic cells, was weaker in HCC tumor tissues than in their peri-tumor counterparts." (PMID 29506567, 2018). "CHD5 is located at 1p36, together with other tumor suppressors including p73, CAMTA1, miR-34a, KIF1β, and CASZ1." (PMID 26943038, 2016). "In-silico analysis showed that several genes (CASZ1, IL1RAPL1, SOX17, N4BP1 and ARHGDIA) suggested to have tumor suppressive functions were target genes of miR-151." (PMID 22928040, 2012). "The expression of PIK3CD was significantly lower (P=0.001 after Bonferroni correction), in unfavourable tumours as compared to favourable NB (PIK3CD: fold change (fc)=−2.5, P=0.0002; CASZ1: fc=−2.0, P=0.03)." (PMID 17940511, 2007). "According to these results, the expression levels of NR3C2, KLF4, CASZ1, FOXD2, ATOH1, and RORC reduce in CRC and may function as tumor suppressors." (PMID 36344988, 2022). "In addition, MIR206, a key microRNA that regulates skeletal myogenesis and functions as a tumor suppressor in RMS34, was also found to be driven by a SE co-occupied by CASZ1, MYOD and MYOG." (PMID 32060262, 2020). "Consistent with the in vitro results, CASZ1 overexpression in HCCLM3 cells significantly inhibited tumor growth, as evidenced by tumor sizes and weights, whereas knockdown of CASZ1 in PLC/PRF/5 cells markedly increased tumor burden in vivo." (PMID 29506567, 2018). "To further examine whether the tumor-suppressive effects of CASZ1 were dependent on MAPK/ERK pathway, we treated CASZ1-interfered HCC cells with a MEK inhibitor U0126." (PMID 29506567, 2018). "We found that low CASZ1 significantly correlated with aggressive clinicopathologic features, such as larger tumor size, multiple tumor nodules, lack of capsule, higher Edmondson-Steiner grade, advanced BCLC stage and TNM stage, which further proved the suppressive role of CASZ1 in HCC progression." (PMID 29506567, 2018). "However, since only portions of one of the CpG islands in CASZ1 and PIK3CD were methylated, it is not likely that this account for the low expression of the genes in unfavourable tumours." (PMID 17940511, 2007).
cancer (17 papers, 2013 to 2024). A tumor composed of atypical neoplastic, often pleomorphic cells that invade other tissues. "Beyond cancer, loss-of-function mutations in CASZ1 have been associated with susceptibility to human heart diseases, and CASZ1 methylation has been associated with cardiovascular mortality." (PMID 38053207, 2023). "In this review, we discuss the physiological function of CASZ1, and focus on the association of CASZ1 aberrations with the pathogenesis of cardiovascular diseases and cancers." (PMID 37509718, 2023). "Other studies also found CASZ1 mutations or expression aberrations in different cancers, but the effect on cell behavior and cancer progression remains elusive." (PMID 37509718, 2023). "The loss of CASZ1 expression or its mutational inactivation is associated with diseases or cancers linked to developmental defects." (PMID 38053207, 2023). "Taken together, CASZ1 induces skeletal muscle differentiation program in both myoblasts and ERMS, however, CASZ1 preferably regulates normal development processes in myoblasts and genes associated with cancer progression in ERMS." (PMID 32060262, 2020). "Sometimes CASZ1 can adopt different mechanisms but cause similar outcomes in cancer progression." (PMID 37509718, 2023). "Studies have revealed the association of CASZ1 with multiple cancer types." (PMID 37509718, 2023). "Moreover, mutations and aberrant expression patterns of CASZ1 might be causative of cancer development, suggesting the potential of a future application as a prognostic indicator." (PMID 37509718, 2023). "Differential regulatory mechanisms in different cancers are suggested by the variability of CASZ1 expression across distinct solid tumors." (PMID 39235847, 2024). "The involvement of the Castor zinc finger 1 (CASZ1) gene in adverse prognostic outcomes has been observed across different cancer types." (PMID 39235847, 2024). "Mechanistically, the impact of CASZ1 on cancer cell behaviors is attributed to its regulation of genes commanding proliferation, differentiation, or adhesion." (PMID 37509718, 2023). "CASZ1 is differentially expressed in various cancer types and plays “double-agent” roles in their progression." (PMID 37509718, 2023). "Studies have also characterized the involvement of CASZ1 in disease conditions, mostly cardiovascular disorders and cancers." (PMID 37509718, 2023). "There is potential to apply CASZ1 in the prenatal genetic examination of CHDs and pediatric tumors or as a prognostic indicator for cancers." (PMID 37509718, 2023). "CASZ1 can be used as a biomarker for disease prevention and diagnosis as well as a prognostic indicator for cancer." (PMID 38053207, 2023). "CASZ1 downstream genes in different cancers include differentiation markers, cell cycle proteins, adhesion molecules and cytoskeleton molecules." (PMID 37509718, 2023). "The expression of FOXS1 in cancer samples increased considerably compared to adjacent normal samples, while the expression of CASZ1 decreased (P < 0.01)." (PMID 36344988, 2022). "First, the GSEA analysis revealed that CASZ1 overexpression was related to cancer‐related signaling pathways, including the “Notch signaling,” “transforming growth factor‐beta (TGF‐β) signaling,” “IL6_JAK_STAT3 signaling,” and “EMT signaling”." (PMID 36276925, 2022). "FOXS1 expression rose in TCGA and GSE39582 cancer samples, but CASZ1 expression dropped, according to the results of the preceding steps." (PMID 36344988, 2022). "Castor zinc finger 1 (CASZ1) plays critical roles in various biological processes and pathologic conditions, including cancer." (PMID 29506567, 2018). "We further investigated the effect of CASZ1 on the expression of several genes related to cancer cell proliferation and invasion, such as MMP2, MMP9, cyclinD1 and epithelial-mesenchymal transition (EMT) genes, which were controlled by the MAPK/ERK pathway." (PMID 29506567, 2018).
cancer (continued). "To probe the molecular mechanism underlying CASZ1-mediated inhibition of HCC growth and metastasis, we performed a Cignal Finder Cancer 10-Pathway Reporter Array in CASZ1 overexpression or knockdown HCC cells." (PMID 29506567, 2018). "Given the potential significance of CASZ1 in cancer pathobiology, its clinical relevance and potential role in human HCC deserves to be investigated." (PMID 29506567, 2018). "The cumulative effect analyses by considering multiple CpG sites in each gene also demonstrated an obvious difference of methylation levels between normal and cancer samples (CASZ1: P 0.001, CDH13: P 0.001, ING2: P 0.001)." (PMID 30355852, 2018). "Clustered T-UCRs localized in the intronic region of CASZ1 are differentially expressed in cancer cells and are members of the BlCa signature: uc.3+, uc.4+, and uc.5+ expression is downregulated and uc.8+ expression is upregulated in BlCa tissue." (PMID 26943042, 2016). "Hence, investigating the prognostic value of CASZ1 as a biomarker for cancer diagnosis and prognosis is imperative." (PMID 38053207, 2023). "In addition to its crucial role in both neural and cardiac development, the involvement of CASZ1 in various pathological conditions, including cancer, is being increasingly recognized." (PMID 38053207, 2023). "However, these processes are possibly impaired in various cardiovascular diseases and cancers due to CASZ1 genetic or expression aberrations." (PMID 37509718, 2023). "Over the past decades, at first glance, paradoxical influences on cell behaviors and progressions of different cancer types have been discovered for CASZ1, which may be explained by a “double-agent” role for CASZ1." (PMID 37509718, 2023). "Therefore, it is likely that CASZ1 enhances the migration property of carcinomas, while it inhibits that in sarcomas." (PMID 37509718, 2023). "In carcinoma cells, CASZ1 upregulates the genes for cell migration or invasiveness, represented by ITGAV, which encodes integrin subunit αV for fibronectin or vitronectin interactions, and α-SMA-encoding actin stress fiber that is essential for EOC cell motility." (PMID 37509718, 2023). "We noticed that overexpressed CASZ1 was involved in cancer‐related signaling pathways and multiple immune‐inflammatory signaling pathways, including “B‐cell receptor signaling pathway,” “Toll‐like receptor signaling pathway,” “T‐cell receptor signaling pathway,” and “NF‐Kappa B signaling pathway”." (PMID 36276925, 2022). "The CASZ1/uc.8+ ratio in NBE controls highly favored CASZ1 expression, whereas in cancer patients, the ratio shifted in favor of uc.8+ expression in the different stages of BlCa." (PMID 26943042, 2016). "Noteworthy, T2319 is the only example in our collection of carcinoma samples in which two HPV16 DNA junctions are located in an exon, here in the long 3′-terminal exon of the CASZ1 gene." (PMID 23824673, 2013). "Additionally, CASZ1 is upregulated in EOC cells, promoting their epithelial–mesenchymal transition, whereas CASZ1 knockdown inhibits cancer cell metastasis in vivo." (PMID 38053207, 2023). "We found that CASZ1 might interact with RAF1, a highly-conserved serine/threonine kinase of the MAPK pathway that involved in cell proliferation, transformation, survival and metastasis of various cancers." (PMID 29506567, 2018). "Although CASZ1 was reported to modulate EGFL7/RhoA pathway and pRb activity in different cell types, however, given the context-dependent function of CASZ1 in various cancers, we speculated that CASZ1 may have a different mechanism to counteract HCC growth and metastasis." (PMID 29506567, 2018). "We were not able to validate TMPRSS2 fusions with CASZ1, SIM2, and C1orf61 due to the insufficient amount of RNA; however, all these genes are known to play roles in pathologic conditions, including cancers." (PMID 37300660, 2023).
cardiovascular diseases (3 papers, 2021 to 2023). "Notably, the methylation of CASZ1 serves as a regulatory element associated with mortality in patients with cardiovascular disease, and it is reported hypomethylated in Chinese patients with hypertensive cerebral infarction." (PMID 38053207, 2023). "An epigenome-wide association study, leveraging genome-wide transcriptome data, has revealed that CASZ1 methylation may serve as a regulatory element linked to mortality in patients with cardiovascular disease." (PMID 38053207, 2023). "Future studies should explore whether CASZ1 regulates immune cell activities, such as cytokine productions or Th17 cell conversions in cardiovascular diseases." (PMID 37509718, 2023). "Seven of these DMPs (25%) could be allocated to a gene that was previously associated with cardiovascular diseases (HDAC4, IGF2BP3, CASZ1, SDK1, PCDHGA1, DIO3, PTPRN2)." (PMID 34895303, 2021).
cardiac disease (2 papers, 2017 to 2023). "Associating CASZ1 loss-of-function mutations with human cardiac disease susceptibility holds potential implications for the personalized prevention and treatment of cardiac diseases." (PMID 38053207, 2023).
infection (2 papers, 2018 to 2025). The state of being infected such as from the introduction of a foreign agent such as serum, vaccine, antigenic substance or organism. "Interestingly, there was a slight, but significant delay in recovery from infection-dependent body weight loss in Casz1 knockout mice, albeit both the control and Casz1 knockout groups eventually recovered." (PMID 29467767, 2018). "Also, absence of Casz1 caused a significant diminution in IFN-γ+IL-17A+ iTh17 cells (Th1*) in draining LN and tongue during secondary infection." (PMID 29467767, 2018).
metabolic disease (1 paper, 2023). A congenital disorder (due to inherited enzyme abnormality) or acquired (due to failure of a metabolically important organ) disorder resulting from an abnormal metabolic process. "Abnormal DNAm levels at the promoter of CASZ1 gene in the placental may lead to metabolic diseases, including T2DM." (PMID 37461060, 2023).
CASZ1 also shares sentences with these, for which no sentence is quoted: breast carcinoma (2 papers); left ventricular noncompaction (2); ovarian cancer (2); Alzheimer disease (1); atopic dermatitis (1); bladder cancers (1); cardiac arrhythmia (1); cataract (1); cognitive defects (1); colorectal (1); congenital heart defects (1); dementia (1); demyelinating disease (1); developmental delay (1); esophageal squamous cell carcinoma (1); hyperlipidemia (1); Intellectual disability (1); liver steatosis (1); metastatic tumors (1); migraine (1); multiple sclerosis (1); Noncompaction cardiomyopathy (1); oral squamous cell carcinomas (1); Osteochondrosis (1); prostate carcinoma (1); ptosis (1); retroperitoneum (1); Telangiectasia (1); urothelial carcinoma (1).